MTOR (mechanistic target of rapamycin kinase)
Diseases named in the same sentence as MTOR in open-access papers (continued):
Sharing a sentence is not in itself a finding about the gene and the disease.
cancer (continued). "To demonstrate that in a specific example, we selected and analyzed the PI3K/AKT/mTOR pathway, which is in the regulation of cell apoptosis and a target of many cancer drug discovery studies." (PMID 25324859, 2014). "Metformin treatment leads to energy stress and AMPK activation in cancer cells, which can impair proliferation by suppressing anabolic processes and growth signaling through mammalian target of rapamycin (mTOR)." (PMID 25347702, 2014). "mTOR inhibitors are also clinically tested for the treatment of cancers and neurogenetic disorders, such as tuberous sclerosis." (PMID 25015322, 2014). "The over-activated PI3K/Akt/mTOR pathway, because of its essential role in promoting cancer growth and survival, is deemed one of the most promising signaling pathways to target for therapeutic intervention." (PMID 25334061, 2014). "A significant energy regulating effect of AMPK pertaining to cancer therapeutics is the ability of AMPK to inhibit the mTOR pathway." (PMID 24628795, 2014). "The PI3K/Akt/mTOR pathway is an important intracellular signaling pathway in regulating cell growth, survival, adhesion and migration, particularly during cancer progression, metastasis and radioresistance, and is frequently activated in cancer cells." (PMID 25275598, 2014). "Our data identifies potential cross-talk between AMPK, mTOR and 4EBP1 as important mediators of altered lipid metabolism in cancer cachexia." (PMID 24667661, 2014). "As the phosphatidyl-inositol-3-kinase (PI3K)/Akt/mammalian target of rapamycin (mTOR) pathway is aberrantly activated in many tumour types, mTOR suppression is regarded to be an attractive approach for cancer therapy." (PMID 24779401, 2014). "Active-site mTOR inhibitors (asTORi) are a novel class of anti-cancer drugs that suppress both rapamycin-sensitive and rapamycin-resistant functions of TORC1 and TORC2." (PMID 24586420, 2014). "HDAC- plus mTOR inhibition was also highly effective in stopping the metastatic activity of cancer cells." (PMID 24779401, 2014). "So far, several statuses of the effectors on the upstream and downstream of mTOR pathway such as amplification of a catalytic subunit of PI3K and loss or mutation of PTEN gene have been detected in many malignant tumors." (PMID 24818169, 2014). "Inhibition of MTOR that leads to autophagy activation has been demonstrated as a therapeutic approach for cancers in many studies." (PMID 25375091, 2014). "The phosphoinositide 3-kinase (PI3K)/mammalian target of rapamycin (mTOR) pathway is very frequently activated in human cancer by a variety of genetic and epigenetic events." (PMID 24795861, 2014). "A number of pan- and isoform selective PI3K inhibitors have been developed and are under current investigation for the treatment of cancers where the PI3K/Akt/mTOR pathway is central to the transformed phenotype of most cancer cells." (PMID 25460003, 2014). "These mutations are thought to lead to activation of RHEB, which in turn promotes activation of the mTOR gene, one downstream effect of which is vastly increased protein production and much larger cancer cells." (PMID 25041817, 2014). "LAM is associated with inappropriate activation of mammalian target of rapamycin (mTOR), an important intracellular pathway that is also deregulated in cancer cells." (PMID 24995140, 2014). "The activation of mTOR can confer many growth advantages to cancer stem or progenitor cells such as promoting cell proliferation and resistance to apoptosis induced by various stress signals such as hypoxia and nutrient deficiency." (PMID 24804240, 2014). "Elevated mTOR activity is a prominent feature of cancer cells, including hematological malignancies." (PMID 24586420, 2014).
cancer (continued). "The toxic side effects and drug resistance obstacles encountered greatly limit the use of single agents as monotherapies to target the PI3K/Akt/mTOR pathway in cancer treatment." (PMID 25334061, 2014). "The expression rate of mTOR of cancer tissue was the highest (62.9%) and there were statistically significant differences among normal esophageal, dysplasia, and cancer tissues (P < 0.05)." (PMID 24818169, 2014). "The mammalian target of rapamycin (mTOR) has emerged as a potential target for drug development, particularly due to the fact that it plays such a crucial role in cancer biology." (PMID 24393708, 2014). "The PI3K/Akt/mTOR pathway represents a good example of the concept of redundancy in biological systems, particularly in cancer cells." (PMID 24782981, 2014). "Reactivating mTOR by MHY1485 protected cancer cells from OA-mediated decline in PKM2 expression and increase in PKM1 levels." (PMID 24626155, 2014). "We have shown that growth of cancer cells unresponsive to an allosteric mTOR inhibitor can still be sensitive to mTOR kinase blockade, with AZD8055 substantially inhibiting growth in TamR and MCF7-X cells (IC50 18 and 24 nM, respectively)." (PMID 24457069, 2014). "mTOR is the key molecule that regulates cancer growth and the process of aging both in the presence or absence of CR." (PMID 25026276, 2014). "Applying this mechanism, a dual-acting compound has been constructed which disrupts cancer networks via potent inhibition of the Akt-mTOR pathway and epigenetic effects of HDAC." (PMID 24779401, 2014). "Greater understanding of the molecular mechanisms at play in oncogenesis, such as the mammalian target of rapamycin (mTOR) pathway, has shown that the interplay between DM and cancer is much more complex than originally thought." (PMID 24879130, 2014). "The metabolic rewiring of cancer cells supporting tumor growth and survival relies on a hierarchical oncogenic cascade involved in Akt/mTOR, MAPK, and essential transcriptional factors, such as HIF1α- and Myc-dependent metabolic transcriptome." (PMID 25120544, 2014). "Inhibition of MTOR leading to autophagy activation has been demonstrated as a therapeutic mechanism for various cancer types." (PMID 25375091, 2014). "Accumulating evidences have demonstrated that mTOR has a central role not only for cell growth but also for invasion and metastasis of cancers." (PMID 24818169, 2014). "Cancer therapies that simultaneously target activated mammalian target of rapamycin (mTOR) and cell metabolism are urgently needed." (PMID 25436981, 2014). "Mammalian target of rapamycin (mTOR) is identified as a promising therapeutic target for the treatment of a number of types of cancer." (PMID 27351005, 2014). "mTOR is a serine/threonine-specific kinase that is responsible for mitogen-induced cell proliferation, survival and motility in cancer cells." (PMID 24866893, 2014). "The mammalian target of rapamycin (mTOR) has emerged as a critical effector in cell signaling pathways commonly deregulated in human cancers." (PMID 25134527, 2014). "Several inhibitors that target either PI3K alone or PI3K/mTOR are currently in phase I cancer clinical trials." (PMID 25221930, 2014). "Recently, mTOR signaling has been proven to modulate the metabolic switch in cancer cells and this effect is mediated by the change in PKM2 expression." (PMID 24626155, 2014). "The mTOR inhibitors such as rapamycin and CCI-779 have been tested as anti-cancer drugs, because they inhibit or block mTOR signaling pathway." (PMID 28324458, 2014).
cancer (continued). "mTOR inhibitors exert antitumor effects on several cancers in which the AKT/mTOR pathway is hyperactivated, but their effects are frequently modest in clinical trials." (PMID 25098767, 2014). "The PI3K/Akt/mTOR signaling pathway has an important role in cancer metabolism regulating proliferation and apoptosis." (PMID 24858012, 2014). "The expression rates of mTOR were 20% (3/15), 46.7% (7/15), and 62.9% (22/35) in normal esophageal, dysplasia, and cancer tissues, respectively." (PMID 24818169, 2014). "KLT has an inhibitory effect on many kinds of tumors and PI3K/Akt/mTOR signaling promotes cell survival, proliferation, and progression in cancer cells." (PMID 25005526, 2014). "Through crosstalk with Wnt, NF-κB and MAPK pathways, Akt/mTOR activity promotes cancer cell proliferation, inhibition of apotosis and metastasis." (PMID 24505326, 2014). "Increased muscle protein synthesis in response to leucine-induced mTOR activation has been shown to inhibit muscle wasting in mouse models of cancer cachexia and in cancer patients." (PMID 24685128, 2014). "Consistent with a role of mTOR in G1-S transition, mTOR inhibitors have been promising in the treatment of various cancers." (PMID 25594050, 2014). "Metformin can activate the LKB1/AMPK pathway and inhibit cancer cell growth by inhibiting mTOR activity." (PMID 24858012, 2014). "At the molecular level, studies from yeast and in mammalian cell lines, mostly in the context of cancer research, have provided a wealth of information on the basic organization of the mTOR pathway and the roles that Pten and Tsc1 play." (PMID 24574959, 2014). "Activation of mTOR pathway occurs in many cancers and has recently been shown to be correlated with more aggressive disease behavior." (PMID 24818169, 2014). "The EGFR signaling pathway, including its multiple downstream pathways, such as PI3K/AKT, ERK1/2, JAK/STAT3 and mTOR/NF-κB, plays an important role in the regulation of proliferation, survival, migration and chemoresistance in cancer cells." (PMID 24586249, 2014). "Activation of the PI3K/Akt/mTOR pathway is an important feature in many cancers, and inhibitors of this pathway have been developed as anti-cancer drugs." (PMID 25327558, 2014). "Alterations within the PI3K/AKT/mTOR signaling pathway are among the most frequent in human cancers." (PMID 25415047, 2014). "Significant energy regulating effects of AMPK pertaining to cancer therapeutics is its ability to attenuate growth and protein synthesis by regulating mammalian target of rapamycin (mTOR) pathway and induce autophagy." (PMID 24628795, 2014). "Mutation of the tumor suppressor PTEN and activation of PI3K, both of which are common in many kinds of cancers, mediate hyperactivation of mTOR." (PMID 25069390, 2014). "The mammalian target of rapamycin (mTOR) signaling pathway is one of the most important pathways in signal transduction in cancer." (PMID 24866893, 2014). "It is considered that Akt singling stimulates transport and metabolism of both glucose and amino acids, with in turn support mTOR-dependent increases in protein translation in cancer cells." (PMID 24466087, 2014). "Activated Akt in cancer cells can stimulate protein synthesis and consequently cell growth through activation of mTOR, S6 kinase and eukaryotic initiation factor 4E-binding protein 1(4E-BP1)." (PMID 25352949, 2014). "Macro-autophagy has recently emerged as a major cellular process regulated by PI3K signaling that affects response to PI3K/AKT/mTOR inhibitors in both mouse models of cancer and in primary human cancers." (PMID 24599075, 2014). "Studies have shown that both NVP-BEZ235 and GDC-0980 significantly inhibit PI3K and mTOR activity, and tumor growth in many preclinical cancer models." (PMID 25221930, 2014).
cancer (continued). "Our work has significant clinical relevance, as inhibition of mTORC2 has been suggested as a possible therapeutic approach for the treatment of certain cancers, and dual mTOR/PI3K inhibitors are being developed for clinical use." (PMID 25059582, 2014). "The PI3K and AKT pathway, commonly known as PI3K/AKT/mTOR pathway, is perhaps the most frequently dysregulated pathway in human cancers." (PMID 24586269, 2014). "Up-regulation of the PI3K/mTOR (phosphatidylinositol-3′ kinase/mammalian target of rapamycin) signaling is common in carcinoma." (PMID 25298748, 2014). "The targeted inhibition of both glycolysis and mTOR can cooperate to induce severe metabolic deregulation, cell death, and impaired ATP generation in cancer cells that are more dependent on glycolysis for energy production." (PMID 24024216, 2013). "Dysregulation of mTOR signalling often occurs in a variety of human malignant diseases making it a crucial and validated target in the treatment of cancer." (PMID 23434669, 2013). "They include BEZ-235, SF1126 and XL765, which are more effective than single inhibitors of PI3K or mTOR in cancer therapy." (PMID 23339750, 2013). "For example, miR-100 and miR-199a-3p suppress mTOR expression, and miR-152 and miR-218 suppress Rictor in some cancers." (PMID 24244675, 2013). "Phosphatidylinositol 3-kinase (PI3K)/Akt/mammalian target of rapamycin (mTOR) signaling pathway is extensively explored in cancers." (PMID 24252186, 2013). "The PI3K/Akt/mTOR pathway is constitutively activated in human cancers and is critical for tumor progression and chemo-resistance." (PMID 24252186, 2013). "Usual treatment is surgery for benign tumors and chemotherapy including mTOR inhibitors for malignant tumors." (PMID 24489554, 2013). "mTOR signaling is frequently dysregulated in a number of human diseases including cancer, cardiovascular disease and ageing, and thus has become an attractive target for therapeutic intervention." (PMID 23454868, 2013). "mTOR emerged as a central node in cellular metabolism, cell growth, and differentiation, as well as cancer metabolism." (PMID 23783557, 2013). "The mammalian target of rapamycin (mTOR) inhibitors, a set of promising potential anti-cancer agents, has shown response variability among individuals." (PMID 24009623, 2013). "Pharmacological inhibitors of enzymes in these pathways, such as BRAF inhibitors and mTOR inhibitors, are already being used in clinical settings to treat cancer, while others (PI3K and MEK1 inhibitors) are in advanced stages of clinical trials." (PMID 24078813, 2013). "mTOR inhibitors can have a double-edged sword by activating autophagy, and autophagy itself has a double-edged sword in cancer by the promotion of metabolically stressed tumor cell survival." (PMID 24185040, 2013). "Aggressive cancer cells often take advantage of mitogenic signaling pathways to activate mTOR and free up eIF4E to maintain their survival and growth." (PMID 24180592, 2013). "Current knowledge indicates that miRNAs are involved in regulating the mTOR pathway in some cancer types." (PMID 23434669, 2013). "The PI3K/Akt/mTOR signalling cascade, frequently altered in malignancies, has been found to affect the alternative splicing profile of cancer-relevant genes via Akt-dependent phosphorylation of several SR proteins, such as SRSF1 and SRSF5." (PMID 24078813, 2013). "Similar to ER cells, in untreated SR H2170 cells, we found a marked upregulation (20-fold) of p-p70S6K, a protein downstream of mTOR that is involved in cancer cell survival, and an upregulation was seen in cells treated with HGF and SU11274." (PMID 24223799, 2013). "The mTOR pathway plays an important role in nutrient uptake, regulation of energy metabolism, and cancer cells survival." (PMID 24024216, 2013).
cancer (continued). "Activation of Akt/mTOR pathway is the major regulator of apoptosis resistance and cancer transformation in UVB irradiated skin cells." (PMID 24365180, 2013). "The Akt/mTOR pathway is often dysregulated in malignant cells, thus representing an important target for cancer prevention and therapy." (PMID 23843889, 2013). "Because it plays such a crucial role in cancer biology, mTOR has emerged as a potential target for drug development." (PMID 24185040, 2013). "Previous reports demonstrated that metformin suppressed mTOR signaling by activating AMPK in various cancer cells including HCC cells." (PMID 23922888, 2013). "In the present study, we also showed that IIi induces human cancer cell autophagy, in an identical manner to the mTOR inhibitor, rapamycin." (PMID 23761818, 2013). "For example, these inhibitors likely block mTOR/p70S6K/4E-BP1 survival signals that are usually engaged during PI3K/AKT activation in cancer cells." (PMID 23690929, 2013). "The mechanism of action of metformin involves phosphorylation of LKB-1, which activates AMP-activated protein kinase (AMPK) and consequently inhibits the mammalian target of rapamycin (mTOR) pathway, leading to growth inhibition of cancer cells." (PMID 23291663, 2013). "Because these pathways are commonly dysregulated in cancer, mTOR represents an attractive anti-tumor target." (PMID 23815869, 2013). "FBXW7 acts as a tumor suppressor in numerous types of human cancers through ubiquitination of different oncoproteins including mTOR." (PMID 23454868, 2013). "mTOR can undergo alternative splicing to generate an activated form called mTORbeta which is oncogenic, although its regulation and role in human cancer have yet to be demonstrated." (PMID 24078813, 2013). "The mammalian target of rapamycin (mTOR) pathway is a master regulator of protein synthesis and frequently activated in human cancers." (PMID 25284964, 2013). "AMPK and its downstream molecule mammalian target of rapamycin (mTOR) have been considered as a therapeutic target for cancer treatments." (PMID 23531917, 2013). "mTOR inhibitors are a class of novel targeted agents that have shown promising results in cancer treatment." (PMID 24009623, 2013). "Recently it has been shown that the translation of mRNAs encoding proteins involved in the invasive and metastatic properties of cancer cells is directly regulated by mTOR." (PMID 23940704, 2013). "We also observed the association with cancer related gene sets, such as the MYC down-regulated gene set (miR-17 and miR-18b), as well as gene sets representing mTOR and PTEN pathways (miR-19a/b)." (PMID 24059244, 2013). "A model is presented in this article, which suggests that the PI3K-Akt-mTOR and Wnt pathways converge and regulate the progression of cell cycle through G0-G1-S-phases and reprogram the metabolism in cancer cells." (PMID 23596569, 2013). "Dysregulation of mTOR signaling is frequently observed in many types of cancers, implicating it in promotion of tumor growth and malignancy." (PMID 24244675, 2013). "More importantly, we provide a novel molecular mechanism that further links extracellular ATP-P2X7 signals to the intracellular mTOR pathway, one of the critical control nexuses of signaling transduction networks and used as a cancer therapeutic target." (PMID 23565201, 2013). "It has been well established that the PI3K/Akt/mTOR signaling pathway plays a crucial role in cancer development." (PMID 23420667, 2013). "One should also state that while several nonimmunological mechanistic explanations for the anti-tumour effects of mTOR inhibitors have been described, promotion of immune responses to cancer is unexpectedly coming more into focus." (PMID 24565200, 2013). "Collectively, for the first time we have demonstrated that everolimus inhibits glycolysis, partly by repressing mTOR signaling which then upregulates miR-143, an important cancer-related microRNA involved in the deregulation of HK2." (PMID 23251295, 2013).